PLCB4 (phospholipase C beta 4)
Diseases named in the same sentence as PLCB4 in open-access papers (continued):
Sharing a sentence is not in itself a finding about the gene and the disease.
acute myeloid leukemia (1 paper, 2025). Acute myeloid leukemia (AML) is a group of neoplasms arising from precursor cells committed to the myeloid cell-line differentiation. "Similarly, dysregulation of PLCB4 has been associated aggressive phenotypes in hepatocellular cancer and acute myeloid leukemia." (PMID 40278994, 2025).
African trypanosomiasis (1 paper, 2025). "KEGG pathway enrichment analysis of these shared genes (corrected p < 0.05) revealed significant overrepresentation in glutamatergic synapse (encompassing HOMER1, HOMER2, PLCB4, and ADCY9) and African trypanosomiasis (containing SELE, MYD88, and PLCB4)." (PMID 41153960, 2025).
Alzheimer disease (1 paper, 2014). A progressive, neurodegenerative disease characterized by loss of function and death of nerve cells in several areas of the brain leading to loss of cognitive function such as memory and language. "Among those genes, Apaf1, Bace2, and Plcb4 were enriched in the “Alzheimer's disease-reference pathway” and downregulated after ME intervention." (PMID 25580148, 2014).
cervical cancer (1 paper, 2022). A primary or metastatic malignant neoplasm involving the cervix. "The results showed that PLCB4, FBLN5, TSPAN8, CST6, and SERPINB7 were highly expressed in cervical cancer tissues (p<0.05)." (PMID 36408178, 2022).
depression (1 paper, 2021). "In the restrained group, genes involved in long-term depression (Plcb4, Gucy1a3, Prkg2, Ppp1r17, Grid2, and Crhr1) were downregulated compared to the control group." (PMID 34276303, 2021).
glioma (1 paper, 2025). A benign or malignant brain and spinal cord tumor that arises from glial cells (astrocytes, oligodendrocytes, ependymal cells). "To explore the molecular mechanisms underlying this association, we established a U87 glioma cell line with lentiviral-mediated PLCB4 overexpression and performed high-throughput RNA sequencing." (PMID 40852729, 2025). "Consistent with findings by Waugh, PLCB4 was significantly downregulated in various cancers, including glioma." (PMID 40852729, 2025). "Immunohistochemical analysis of patient tumor samples revealed a significant inverse correlation between PLCB4 expression and glioma malignancy, aligning well with our previous bioinformatic predictions." (PMID 40852729, 2025).
insomnia (1 paper, 2011). A sleep disorder characterized by difficulty in falling asleep and/or remaining asleep. "Hence, dysregulation of ROR1, PLCB1, or PLCB4 by PAX6 and CTCF may be one mechanism that links neural and pancreatic dysfunction not only in insomnia but also in the relevant psychiatric disorders that are accompanied with circadian rhythm disruption and metabolic syndrome." (PMID 21494683, 2011).
leukemia (1 paper, 2019). A malignant (clonal) hematologic disorder, involving hematopoietic stem cells and characterized by the presence of primitive or atypical myeloid or lymphoid cells in the bone marrow and the blood. "Conversely, the PLXND1, PLCB4, HOXA9, HOXA10, TLX3, and NKX2‐1 genes had higher expression in the CIMP+ subgroup, compared to the normal T cells and CIMP− leukemias." (PMID 30575306, 2019).
liver cancer (1 paper, 2025). An epithelial or non-epithelial malignant neoplasm that arises from the liver. "PLCB4 hypomethylation has been linked to the development of HCC and the survival of liver cancer without recurrence." (PMID 40027133, 2025).
retinal degeneration (1 paper, 2023). Degeneration of the retina. "We explored the light-dependent regulation of Pkc53E and observed a reduced Pkc53E activity accelerates retinal degeneration of norpAP24 mutants that lack PLCβ4, the major PLCβ involved in the visual signaling." (PMID 37201584, 2023). "It is important to note that norpA flies lacking PLCβ4 undergo light-dependent retinal degeneration, which is characterized by the age-dependent reduction in rhabdomeres, a phenotype different from that of pkc53E RNAi." (PMID 37201584, 2023).
Sepsis (1 paper, 2022). Sepsis is defined as life-threatening organ dysfunction caused by a dysregulated host response to infection. "Regarding transcripts of the adrenergic pathway, sepsis decreased the α-adrenergic receptor (α-AR) and phospholipase C beta 4 (PLCB4) expression and increased G protein-coupled receptor kinase 5 (GRK5) that inhibits adrenergic pathways, only in OVR females." (PMID 35322092, 2022).
Stroke (1 paper, 2015). Sudden impairment of blood flow to a part of the brain due to occlusion or rupture of an artery to the brain. "Furthermore, genetic variants in PLCB4/PLC1 have been significantly associated with several phenotypic traits including levels of apolipoprotein B, cholesterol and HDL, along with body weight, body mass index and stroke." (PMID 26434682, 2015).
Thrombosis (1 paper, 2018). "Thrombosis suppression by heterozygous Plcb4 loss of function was confirmed through analysis of an independent, CRISPR/Cas9-induced Plcb4 mutation (p = 0.01)." (PMID 30188893, 2018).
tumor (24 papers, 2016 to 2025). "This association was corroborated in our internal cohort, where PLCB4 expression significantly decreased with increasing tumor grade (WHO IV vs. II/III: p< 0.01)." (PMID 40852729, 2025). "In two patients the tumor harbored a PLCB4 p.Asp630Phe mutation, in one patient there as a CYSLTR2 p.Leu129Gln mutations, and one patient was wildtype for these two genes as well." (PMID 34771480, 2021). "To explore the implications of lipid catabolism-associated genes in gastrointestinal stromal tumors, we reappraised transcriptomic and genomic datasets and identified copy-gained and differentially upregulated PLCB4 gene associated with tumor progression." (PMID 28212550, 2017). "At the DNA and protein levels, PLCß4 overexpression and PLCB4 copy gain both robustly characterized GISTs featuring increased tumor size, mitosis, and higher risk levels defined by both NIH and NCCN schemes." (PMID 28212550, 2017). "Notably, PLCB4 is strongly associated with aberrant tumor proliferation, making it a compelling therapeutic target." (PMID 40852729, 2025). "Notably, the high mutation frequency of PLCB4 further supported its potential role as a tumor suppressor gene." (PMID 40852729, 2025). "Compared with normal tissues, PLCB4 mRNA abundance was significantly higher in GISTs as a whole (p<0.001) and also increased from normal tissue over the non-high-risk group (p=0.007) to high-risk GISTs (p=0.008), indicating its implication in tumor progression." (PMID 28212550, 2017). "Among these, in vitro experiments revealed PLCB4 as a novel therapeutic target, with expression inversely correlated with tumor grade." (PMID 40852729, 2025). "High expression of PLCB4 in tumor tissues, malignant cells, and endothelial cells correlates with its role in promoting tumor proliferation and angiogenesis." (PMID 39895793, 2025). "We examined the expression levels of CDKN2A, NXPE4, and PLCB4 in normal and tumor tissues using data from the TCGA database." (PMID 39895793, 2025). "Transcriptomic data from 36 tumor types identified PLCB4 as a protective factor in more than 10 cancers." (PMID 40852729, 2025). "The mutant allele abundance increased with tumor progression, while an increase in the wild-type allele frequency has been observed in UM tumors with mutations in GNAQ, GNA11 or PLCB4, indicating a complex relationship between these genetic alterations." (PMID 38920653, 2024). "All but one tumour have a known UM driver gene mutation (GNAQ, GNA11, BAP1, PLCB4, CYSLTR2, SF3B1, EIF1AX)." (PMID 32415113, 2020). "Most UMs harbor one Gq pathway mutation (GNAQ, GNA11, CYSLTR2, or PLCB4), one BSE mutation (BAP1, SF3B1, or EIF1AX), and a few recurrent CNAs, in 100% of tumor cells." (PMID 29317634, 2018). "In this context, we selected PLCB4 to validate its clinical relevance in two independent tumor cohorts." (PMID 28212550, 2017). "In a clinical setting where tumor tissue is unavailable, comprehensive screening for all oncogenic mutations in both paralog genes GNAQ and GNA11 as well as in CYSLTR2 and PLCB4, would be necessary to improve the detection rate of tumor-derived DNA in ocular fluids." (PMID 40461505, 2025). "Multi-omics analyses revealed that PLCB4 is frequently amplified and mutated at the genomic level across several GBM patient cohorts, yet its expression is consistently downregulated, indicating its potential role as a tumor suppressor." (PMID 40852729, 2025). "Frequent mutations in PLCB4 have been identified in GBM, leading to pro-oncogenic signaling and trafficking defects that may confer a survival advantage during tumor progression." (PMID 40852729, 2025). "Analysis of tumour biopsies (n = 63) showed that 61 (97%) had likely loss of one copy of BAP1, 23 (37%) had mutations in the gene encoding GNAQ, 26 (41%) in GNA11, three (5%) in CYSLTR2, one (2%) in PLCB4 and 11 (17%) in SF3B1." (PMID 36229663, 2022).
tumor (continued). "Assessment of known UM driver genes revealed an oncogenic driver mutation in 102 of 103 tumours: 51 in GNAQ (48 p.Q209P/L, two p.R183Q, one p.G48L), 46 in GNA11 (44 p.Q209L/P, two p.R183C), five in PLCB4 (three p.D630Y, two p.D630N) and two in CYSLTR2 (p.L129Q)." (PMID 32415113, 2020). "As a proof of concept, we corroborated the clinical relevance of the increased dosage effect of PLCB4 gene in human neoplasms for the first time, highlighting the presumable conversion of copy gain into upregulated mRNA and overexpressed protein in an aggressive subset of GISTs." (PMID 28212550, 2017). "These genomic alterations suggest that PLCB4 may function upstream in tumor regulatory pathways." (PMID 40852729, 2025). "In summary, PLCB4 and NXPE4 exhibit distinct expression patterns and functions across various CRC tissue and cell types, reflecting their complex and dual roles in tumor biology." (PMID 39895793, 2025). "The expression of FGFR3, PLCB4, and IKBKB were downregulated in the tumor tissues as compared to the adjacent normal tissues." (PMID 31729423, 2019). "Results showed increased levels of CDKN2A and PLCB4 in tumor tissues, whereas NXPE4 expression was higher in normal tissues." (PMID 39895793, 2025). "Phospholipase Cb4 (PLCB4) showed a negative correlation with tumor grade in clinical samples, suggesting its potential role as a tumor suppressor." (PMID 40852729, 2025). "In terms of the genes that are exclusively affected by tumor-specific somatic TE insertions, we also observed the enrichment of affected genes in the cancer pathway (due to tumor-specific TE insertions in genes such as COL4A6, PLCB4, ARNT2, LRP5, NCOA3, and CTNNA2)." (PMID 35013466, 2022). "The analysis of the corresponding tumor and non-tumor samples also revealed upregulation of COMP, matrix proteins such as COL5A1, COL11A1, and FN1, and genes of the Wnt pathway (WNT7B, FZD10, SFRP2), while PLCB1, CAMK2B, PLCB4 and WIF1 are downregulated." (PMID 33227073, 2020).
cancer (16 papers, 2016 to 2025). A tumor composed of atypical neoplastic, often pleomorphic cells that invade other tissues. "Collectively, these studies underscore the multifaceted role of PLCB4 across cancer types and highlight its promise as a target for cancer immunotherapy." (PMID 40852729, 2025). "Protein-level analyses in nine cancer types revealed decreased expression of PLCB4, SOD3, and THRA, alongside increased expression of HMGB2 and RAC2, relative to normal tissues." (PMID 40852729, 2025). "Our results demonstrated that hsa-miR-1271-5p/PLCB4 in the pathway in cancer could be a new potential therapeutic target for mCRC with OXA resistance." (PMID 36927770, 2023). "PLCB4 is highly expressed in a variety of tumors and leads to a poor prognosis in cancer patients." (PMID 36387195, 2022). "Finally, module 4 included the genes PLCB4, MMP1, CTNNB1, EGF, F2R, and LPAR4, associated with pathways in cancer, Rap1 signalling pathway, and phospholipase D signalling pathways." (PMID 31178673, 2019). "Indeed, knockdown of PRDX6, PLCβ4 or STX12 in five additional cancer cell lines similarly affected DTP formation." (PMID 27484502, 2016). "However, this study also shows unexpected up-regulation of crucial genes and kinases (e.g., ERBB4, PLCβ4, PRKAR2B, and PDGFA) whose roles in cancer development and progression are crucial." (PMID 36430510, 2022). "Moreover, several mRNAs in the ceRNA network were enriched in pathways involved in cancer such as WNT11, FGFR3, PLCB4, and IKBKB." (PMID 31729423, 2019).
brain disorder (2 papers, 2020 to 2022). A disease affecting the brain or part of the brain. "In fact, dysregulation of PLCB4 signaling has been suggested to be linked to various brain disorders which may indicate contribution of phospholipase C β 4 deficiency to neurodegeneration in MPS." (PMID 32886284, 2020).
CNS neoplasms (2 papers, 2022 to 2024). "Additionally, molecular analysis of PLCB4 and CYSLTR2 and methylation profiling are especially useful in discriminating these lesions from other pigmented CNS tumors." (PMID 36497333, 2022).
infection (2 papers, 2008 to 2022). The state of being infected such as from the introduction of a foreign agent such as serum, vaccine, antigenic substance or organism. "Lentiviral infection is used to introduce small hairpin RNAs to interfere with the translation of the key signaling proteins GRK2, Gαi2, Gαq, PLCβ3 and PLCβ4." (PMID 18818727, 2008).
neurological disease (2 papers, 2012 to 2025). "Previous studies have shown that PLCB4-positive Purkinje neurons in mice exhibit marked transcriptional plasticity during sensorimotor learning, offering mechanistic insight into the differential susceptibility of these neurons to neurological disease." (PMID 40852729, 2025).
adenocarcinoma (1 paper, 2019). A common cancer characterized by the presence of malignant glandular cells. "In contrast, high mRNA expression of PLCB4 was associated with better OS of adenocarcinoma patients." (PMID 31080817, 2019).
PLCB4 also shares sentences with these, for which no sentence is quoted: Kawasaki disease (3 papers); breast cancer (2); gastrointestinal tumors (2); pancreas cancer (2); bladder cancer (1); cancer of the eye (1); cutaneous melanoma (1); endometrial cancer (1); gastric cancer (1); gastrointestinal stromal tumor (1); hematological malignancies (1); hepatocellular carcinoma (1); Huntington disease (1); Hurler syndrome (1); Hypercalcemia (1); Insulin resistance (1); lung adenocarcinoma (1); metabolic syndrome (1); metastatic colorectal cancer (1); metastatic disease (1); non-small cell lung carcinoma (1); Osteopenia (1); pancreatic cancer (1); psoriasis (1); psychiatric disorder (1).